NEURL2 (neuralized E3 ubiquitin protein ligase 2)
Description:
Plays an important role in the process of myofiber differentiation and maturation. Probable substrate-recognition component of a SCF-like ECS (Elongin BC-CUL2/5-SOCS-box protein) E3 ubiquitin-protein ligase complex, which mediates the ubiquitination of proteins. Probably contributes to catalysis through recognition and positioning of the substrate and the ubiquitin-conjugating enzyme. During myogenesis, controls the ubiquitination and degradation of the specific pool of CTNNB1/beta-catenin located at the sarcolemma (By similarity).
Synonyms: C20orf163; dJ337O18.6; FLJ30259; Ozz; Ozz-E3
Tractability: No criterion of Open Targets' tractability assessment is met for any kind of drug.
Gene: Protein-coding gene on chromosome 20 (45,888,625 to 45,891,208, reverse strand). Ensembl gene ENSG00000124257.
Subcellular location: Cytoplasm
Subcellular location (Human Protein Atlas): Vesicles
Pathways (Reactome):
Metabolism of proteins: Neddylation
Gene Ontology:
Molecular function: ubiquitin protein ligase activity
Biological process: myofibril assembly; intracellular signal transduction; protein ubiquitination
Cellular component: cytosol; cytoplasm
Genetic constraint (gnomAD): Loss-of-function variants: 16 observed, 15.31 expected, observed/expected ratio (o/e) 1.05, 90% interval 0.71 to 1.58. The upper end of that interval is the gene's LOEUF score, 1.58, which puts it in group 6 of 6, group 1 being the genes least tolerant of losing a copy. Missense variants: 393 observed, 411.29 expected, observed/expected ratio (o/e) 0.96, 90% interval 0.88 to 1.04. Synonymous variants: 188 observed, 180.54 expected, observed/expected ratio (o/e) 1.04, 90% interval 0.92 to 1.17.
Homologues: Orthologues: chimpanzee NEURL2 (99% identical), macaque NEURL2 (99% identical), dog NEURL2 (93% identical), pig NEURL2 (92% identical), guinea pig NEURL2 (92% identical), mouse Neurl2 (91% identical), rabbit NEURL2 (79% identical), tropical clawed frog neurl2 (62% identical), zebrafish neurl2 (58% identical).
Diseases named in the same sentence as NEURL2 in open-access papers:
NEURL2 is named in the same sentence as 4 diseases in open-access papers, as found by Europe PMC text mining. Sharing a sentence is not in itself a finding about the gene and the disease.
NEURL2 shares sentences with these, for which no sentence is quoted: cancer (1 paper); clear cell renal cell carcinoma (1); colorectal cancer (1); lung adenocarcinoma (1).